PAICS (phosphoribosylaminoimidazole carboxylase and phosphoribosylaminoimidazolesuccinocarboxamide synthase)
Diseases named in the same sentence as PAICS in open-access papers (continued):
Sharing a sentence is not in itself a finding about the gene and the disease.
glioma (continued). "RT‐qPCR and Western blotting methods were performed to determine the expression of PAICS, ERCC1 and XPA genes in glioma tissues." (PMID 34173716, 2021). "To examine how PAICS is playing a role in glioma progression, we performed a GSEA gene enrichment analysis on the GSE4412 samples and found that NER signal pathway enrichment was most significant when PAICS was highly expressed." (PMID 34173716, 2021). "The mechanism of PAICS in glioma is not yet clear and requires further investigation." (PMID 34173716, 2021). "However, the expression and role of PAICS in glioma have never been reported." (PMID 34173716, 2021).
hepatocellular carcinoma (4 papers, 2017 to 2025). A malignant tumor that arises from hepatocytes. "The lncRNA SNHG1, which is involved in several cancers, such as hepatocellular carcinoma and non-small cell lung cancer, was functionally associated with PAICS and IMPDH2 in this subpathway." (PMID 28152521, 2017).
breast tumors (3 papers, 2008 to 2023). "The observed increased cell migration is consistent with an in vivo animal study showing that PAICS depletion could inhibit primary and metastatic breast tumor growth." (PMID 37172090, 2023). "The expression of ABHD11, ADORA2B, E2F1, EZH2, PAICS, SFN and SH3GL1 was significantly higher in grade III than in grade I breast tumors." (PMID 28411283, 2017).
acute myeloid leukemia (2 papers, 2022 to 2023). Acute myeloid leukemia (AML) is a group of neoplasms arising from precursor cells committed to the myeloid cell-line differentiation. "High PAICS expression levels are correlated with the formation of multiple tumors, including breast, bladder, prostate, gastric, colorectal, and lung carcinomas and acute myeloid leukemia." (PMID 37172090, 2023).
adenoma (2 papers, 2021 to 2022). A neoplasm arising from the epithelium. "However, despite the significant upregulation of PAICS in adenoma and carcinoma, we unexpectedly found that stage I tumors showed the highest levels of PAICS and then it was gradually decreased with advancing disease stage in a stepwise manner." (PMID 33596246, 2021). "Also, a metabolic profiling study of CRC revealed that de novo purine synthesis pathway genes, including PAICS, were highly upregulated even in adenomas and early stages of carcinogenesis, induced by Myc." (PMID 33596246, 2021). "Concerning the potential tumor-promoting role of PAICS, transcriptionally induced by Myc in CRC, upregulated PAICS may confer growth advantage to epithelial cells and facilitate adenoma formation and early-stage colorectal carcinogenesis." (PMID 33596246, 2021).
head and neck cancer (2 papers, 2013 to 2023). A primary or metastatic malignant neoplasm affecting the head and neck. "Furthermore, we examined the expression of the DYRK3/PAICS axis in different stages of head and neck cancer to gain insights into the molecular regulatory changes occurring during cancer progression." (PMID 38139175, 2023).
Lung squamous cell carcinoma (2 papers, 2013 to 2024). "The highest level of overexpression was observed in a squamous cell lung carcinoma (SCLC) study, with a 19-fold increase in PAICS mRNA expression compared with normal tissue." (PMID 23717670, 2013).
Oral Squamous Cell Carcinoma (2 papers, 2023 to 2026). "The results obtained from our experimental investigations have provided compelling evidence supporting the critical involvement of DYRK3 and PAICS in oral squamous cell carcinoma (OSCC)." (PMID 38139175, 2023). "This dysregulation of the PAICS/DYRK3 axis serves as a key modulator, influencing treatment effectors and contributing to tumorigenicity, disease progression, and therapy evasion in patients with oral squamous cell carcinoma." (PMID 38139175, 2023). "This novel insight suggests that the dysregulation of the PAICS/DYRK3 axis may contribute to the acquisition of radioresistance and the metastatic potential of oral squamous cell carcinoma." (PMID 38139175, 2023). "This knowledge opens new avenues for further research on the PAICS/DYRK3 axis as a potential therapeutic target and may ultimately contribute to the development of novel treatment strategies for patients with oral squamous cell carcinoma." (PMID 38139175, 2023).
pancreatic ductal adenocarcinoma (2 papers, 2022 to 2023). An infiltrating adenocarcinoma that arises from the epithelial cells of the pancreas. "For instance, depletion of PAICS suppressed the proliferative and invasive abilities of pancreatic ductal adenocarcinoma cells." (PMID 35379785, 2022). "Notably, PAICS is pivotal in pancreatic ductal adenocarcinoma (PDAC) and is thus regarded as a promising therapeutic target due to its susceptibility to small molecule targeting." (PMID 38139175, 2023).
colorectal tumor (1 paper, 2024). "Correspondingly, loss of PAICS is also correlated with poor relapse‐free survival in stage III colorectal tumor patients." (PMID 38463398, 2024).
Fibroadenoma (1 paper, 2023). A benign tumor of the breast characterized by the presence of stromal and epithelial elements. "Fluorescent immunostaining of the PAICS protein showed elevated expression in malignant breast tissues including intraductal and invasive ductal carcinomas as compared to nonmalignant tissue biopsies including adjacent normal breast tissues and fibroadenomas, in both ERα+ and ERα− samples." (PMID 37172090, 2023).
leukemia (1 paper, 2023). A malignant (clonal) hematologic disorder, involving hematopoietic stem cells and characterized by the presence of primitive or atypical myeloid or lymphoid cells in the bone marrow and the blood. "It has been reported for leukemia that targeting PAICS using MRT reduces cell proliferation by inhibiting DNA synthesis and by promoting apoptosis in vitro and in vivo." (PMID 37172090, 2023).
metastatic tumors (1 paper, 2021). "Moreover, metastatic tumors exhibited significantly lower PAICS expression than that of primary tumors." (PMID 33596246, 2021). "Also, metastatic tumors, including liver or lung metastasis, demonstrated a further decrease of PAICS expression compared to primary tumors in the MSK cohort (P<0.0001)." (PMID 33596246, 2021).
osteosarcoma (1 paper, 2021). A usually aggressive malignant bone-forming mesenchymal neoplasm, predominantly affecting adolescents and young adults. "Thus, we conclude that PAICS acts as an oncogene in osteosarcoma and could be used as a potential diagnostic and prognostic marker." (PMID 35096022, 2021). "The expression analysis of PAICS in several cancers (The Cancer Genome Atlas [TCGA]) showed high expression of PAICS in most of the cancers including osteosarcoma (SARC)." (PMID 35096022, 2021). "Potential candidate gene PAICS (phosphoribosyl aminoimidazole carboxylase, phosphoribosyl aminoimidazole succino carboxamide synthetase) was chosen for further studies in osteosarcoma cell lines for its role in cell proliferation, migration and apoptosis." (PMID 35096022, 2021). "Based on current results, knockdown of PAICS in osteosarcoma cells (HOS and MG-63) significantly reduced the cell proliferation, migration, and wound healing ability and induced apoptosis, which revealed the oncogenic role of PAICS in the osteosarcoma." (PMID 35096022, 2021).
Sepsis (1 paper, 2021). Sepsis is defined as life-threatening organ dysfunction caused by a dysregulated host response to infection. "Our PPI network analysis further unveils several key regulators like TOP2A, PAICS, HSPE1, HSP90AA1 and ACACA in the central hubs of dysregulated gene network in sepsis-induced ARDS." (PMID 33904373, 2021).
cancer (33 papers, 2010 to 2025). A tumor composed of atypical neoplastic, often pleomorphic cells that invade other tissues. "Phosphoribosylaminoimidazole succinocarboxamide synthetase (PAICS), an enzyme involved in this pathway, is essential for DNA synthesis and has been linked to the progression and metastasis of cancer." (PMID 38139175, 2023). "Overexpression of PAICS has been linked to aggressive phenotypes in various cancers." (PMID 40699765, 2025). "Moreover, based on GSEA analysis from the RNA‐sequencing database, epithelial to mesenchymal transition (EMT), coagulation, and angiogenesis, the three major characteristics related to malignant tumors, decreased in PAICS deficiency EGFR wild‐type NSCLC cells." (PMID 38463398, 2024). "Two candidates ADE2 (or PAICS) and Twist-1 are known to be associated with human cancers." (PMID 31841561, 2019). "Alterations in PAICS expression in humans are associated with various types of cancer." (PMID 30097015, 2018). "Moreover, some PCGs, such as IMPDH2, RRM2, and PAICS, involved in this subpathway region are closely associated with colorectal or other types of cancer." (PMID 28152521, 2017). "What is more, cancer patients with genetic alteration of PAICS showed a poor prognosis in OS, PFS, DSS, and DFS." (PMID 38463398, 2024). "PAICS has been shown to exhibit high expression levels across various cancer types and is a prognostic indicator for unfavorable patient outcomes." (PMID 38463398, 2024). "Some enzymes in this pathway (PPAT, PAICS) are expressed at higher levels in specific types of cancer." (PMID 37628755, 2023). "The silencing of PAICS in CRC cells resulted in reduced cancer cell proliferation, colony-forming, invasion, and spheroid-forming capacity." (PMID 32218208, 2020). "The results indicated that PAICS was significantly overexpressed in various cancer tissues, including GC." (PMID 32632107, 2020). "Of note, purine biosynthesis and PAICS expression exhibited strong positive correlation with growth rate of the NCI-60 panel of cancer cell lines, confirming the relevance of this pathway for cancer cell proliferation." (PMID 27721378, 2016). "Cancer cells rely on the PAICS-dependent metabolic pathway for AMP and GMP synthesis, while untransformed cells recover purines via the salvage pathway (and references herein)." (PMID 23717670, 2013). "Moreover, it was further confirmed that the three major characteristics of malignant tumors (EMT, coagulation, and angiogenesis) dramatically decreased in PAICS deficiency EGFR wild‐type NSCLC cells." (PMID 38463398, 2024). "Human PAICS is a promising target forthe treatment of various types of cancer, and it is therefore of highinterest to develop a detailed understanding of its reaction mechanism.In the present work, density functional theory calculations are employedto investigate the PAICS reaction mechanism." (PMID 35914774, 2022). "A detailed understanding of the catalytic mechanismof eukaryoticbifunctional PAICS and the molecular structure of intermediates andtransition states is of crucial importance for emerging cancer therapiestargeting human PAICS, because it can aid the rational design of novelPAICS inhibitors." (PMID 35914774, 2022). "Our results showed that PAICS is a cancer‐promoting gene that is up‐regulated in tumours and PAICS may promote cancer cells proliferation and migration through inhibiting NER pathway." (PMID 34173716, 2021). "Likewise, the same group reported that PAICS expression was significantly higher in tumor tissues than that of their normal counterparts in several cancer types." (PMID 33596246, 2021). "Moreover, we found that MYCN mediated the folate cycle via MTHFD2, which contributed one-carbon unit to enhance purine synthesis, and further regulated nucleotide production by PAICS in response to cancer progression." (PMID 31624245, 2019). "PAICS catalyzes steps 6 and 7 of purine biosynthesis required for proliferation of cancer cells." (PMID 24555823, 2013).
cancer (continued). "Our hypothesis posits that the cancer-inducing role of PAICS/DYRK3 could be instrumental in fostering radioresistance and metastasis in OSCC by boosting the functionality of the purinosome, which in turn enhances the stemness, tumorigenicity, and drug resistance of OSCC." (PMID 38139175, 2023). "Furthermore, a number of prior studies have elaborated on the role of PAICS in several cancers." (PMID 35379785, 2022). "We speculate that SPI1 can play a role in promoting cancer through PAICS." (PMID 35361282, 2022). "However, in the analysis of stage III patients, negative-PAICS expression was significantly associated with worse cancer-specific survival (P = 0.0049)." (PMID 33596246, 2021). "Pan-cancer analysis revealed that purine biosynthesis enzymes, such as PPAT and PAICS, were significantly upregulated in LUAD and LUSC, underscoring the critical role of purine metabolism in NSCLC." (PMID 40699765, 2025). "This suggests that concurrent loss of PAICS and other genes located at chromosome 4q may cooperatively contribute to CRC progression via dysregulation or impairment of key molecular mechanisms in cancer, for instance, cell cycle, cell division, DNA repair, and mitosis." (PMID 33596246, 2021). "Previous studies indicated that PPAT and PAICS were highly expressed in various cancers at advanced stages and involved in progression, which led to proposals for PPAT and PAICS as therapeutic inhibition targets." (PMID 34070461, 2021). "In CRCs, PAICS is involved in regulating the EMT, which is involved in regulation of cancer cell invasion and metastasis." (PMID 32218208, 2020). "Consistent with RNA expression, immunoblot analyses of PPAT, PAICS and PKM2 showed increased expression in cancer tissues compared to normal lung." (PMID 26140362, 2015). "Recently SAICAR, the intermediate metabolite of the enzyme PAICS was shown to allosterically activate PKM2 activity under glucose depleting conditions and mediate ERK1/2 phosphorylation thereby induces cancer cell proliferation." (PMID 26140362, 2015). "PAICS facilitates FAK phosphorylation, which is involved in promoting EMT in cancer cells." (PMID 40699765, 2025). "This influence might specifically alter the glycolysis process involving PAICS and PPAT, thereby impacting the overall metabolic profile and behavior of cancer cells." (PMID 38139175, 2023). "Kaplan-Meier analysis indicated that PAICS protein expression had no prognostic impact on cancer-specific survival in stage II patients (P = 0.6423)." (PMID 33596246, 2021). "Furthermore, our studies with mice reported the role of PAICS in metastasis for the first time and showed less CRC metastasis upon PAICS knockdown in cancer cells." (PMID 32218208, 2020). "PAICS appears to be regulated by MYC in other cancer types, which further emphasizes the important roles this enzyme may play in cancer." (PMID 25869206, 2015). "PAICS, along with PPAT (phosphoribosyl pyrophosphate amidotransferase), another enzyme in the purine biosynthesis pathway, are thought to be key drivers in the metabolic reorientation of cancer cells towards aerobic glycolysis, commonly known as the Warburg Effect." (PMID 38139175, 2023). "Phosphoribosylaminoimidazole carboxylase, phosphoribosylaminoimidazole succinocarboxamide synthetase (PAICS) is an enzyme of the purine biosynthesis pathway and correlated with upregulated cancer phenotypes such as proliferation and invasion in multiple cancer types." (PMID 34925463, 2021). "Notably, 29.0% of tumors lacked PAICS staining, and PAICS-negative expression in tumor had significant prognostic impact on poor cancer-specific survival in stage III CRC." (PMID 33596246, 2021). "However, subsequent analysis revealed that PAICS expression was not correlated with cancer stage, subtype, or TNM stage." (PMID 32632107, 2020). "On the other hand, PAICS has not been assessed as a potential biomarker in any cancer previously." (PMID 25869206, 2015).
cancer (continued). "Other predicted blood-secretory marker proteins such as PAICS, CHRDL1, KLF2, COL10A1 and MYL9 have not heretofore been reported to be cancer related." (PMID 21060876, 2010). "Furthermore, we identified that in cancer patients with genetic alteration of PAICS showed a poor prognosis in OS (p = 5.08e−12), PFS (p = 5.16e−3), disease‐specific survival (DSS) (p = 3.003e−3), and disease‐free survival (DFS) (p = 0.0131), compared with patients without PAICS alterations." (PMID 38463398, 2024).